ENSG00000288636 (novel  protein)
Gene: Protein-coding gene on chromosome 1 (17,005,068 to 17,011,757, reverse strand). Ensembl gene ENSG00000288636.
Genetic constraint (gnomAD): Loss-of-function variants: 13 observed, 15.9 expected, observed/expected ratio (o/e) 0.82, 90% interval 0.53 to 1.3. Missense variants: 143 observed, 148.53 expected, observed/expected ratio (o/e) 0.96, 90% interval 0.84 to 1.11. Synonymous variants: 53 observed, 54.29 expected, observed/expected ratio (o/e) 0.98, 90% interval 0.78 to 1.23.